CCR6 (C-C motif chemokine receptor 6)
Diseases named in the same sentence as CCR6 in open-access papers (continued):
Sharing a sentence is not in itself a finding about the gene and the disease.
COVID-19 (continued). "In the peripheral blood of patients recovered from COVID-19, the proportion of CXCR3+CCR6– Tfh1 and CXCR3–CCR6– Tfh2 cells increased compared to the control, while the CXCR3–CCR6+ Tfh17 cell count was significantly reduced." (PMID 35632823, 2022). "Similar results were obtained using molecular biology methods; in particular, it was shown that the expression of Th17-associated genes decreased in peripheral blood CD4+ T cells of patients with severe COVID-19, as exemplified by RORC, IL17A, IL17F and CCR6." (PMID 35216349, 2022). "On the other hand, the levels of memory CD8+CXCR3+CCR6+ and CD45RO+CXCR3−CCR6+CD8+ T cell subsets were elevated in mild vs. moderate-to-severe COVID-19 patients." (PMID 36146713, 2022). "According to our data, convalescent patients with mild and moderate COVID-19 formed a broad spectrum of SARS-CoV-2-specific CD4+ T cell subsets, but they predominantly expressed CCR6 and were capable of inducing type 3 immunity on mucosal tissues." (PMID 36146622, 2022). "Recently, the frequency of CXCR3+CCR6− cTfh1 and CXCR3–CCR6− cTfh 2 cells was found to be higher in COVID-19 convalescent patients than in healthy donors, whereas the levels of CXCR3–CCR6+ cTfh17 cells in COVID-19 convalescent patients were decreased." (PMID 34696395, 2021). "In severe COVID-19 patients, the frequencies of CCR6+cTfh cells and CCR4+cTfh cells were expanded, but CCR3+cTfh cells and Th1 cells were low in severe COVID-19 patients compared to healthy individuals." (PMID 34603308, 2021). "CD4+ T-cells in the COVID-19 group also had higher expression levels of the activation markers OX40 and CD69, as well as the chemokine receptors CCR6 and CCR4, than the other respiratory infection group, implying a stronger activation." (PMID 34835045, 2021). "Moreover, in patients with COVID-19, the majority of SARS-CoV-2-specific Tfh cells had Tfh17 CCR6+CXCR3– phenotype." (PMID 36012146, 2022). "Indeed, the expressions of CCR6 and its sole ligand, CCL20, were both enriched in the lungs of mechanically ventilated COVID-19 patients." (PMID 35992306, 2022). "Nevertheless, an increased number of CCR6+ cells was noticed in ‘naïve’ and TEMRA CD8+ T cell subsets from COVID-19 convalescents compared to healthy controls (1.76% (1.26; 2.96) vs. 1.16% (0.69; 1.89) and 11.40% (3.27; 20.37) vs. 4.99% (1.39; 10.15), respectively, p < 0.001 in both cases)." (PMID 36146713, 2022). "COVID-19 patients show a substantial reduction in the numbers of peripheral CD4 and CD8 T cells, with the remaining cells exhibiting a hyperactivated status (CD38+ HLA-DR+) and are enriched for pro-inflammatory C-C chemokine receptor 6 (CCR6+) Th17 T cells." (PMID 33302366, 2020). "In addition, flow cytometric analysis of a blood sample from this COVID-19 patient revealed that CD4 and CD8 T-cells were hyperactivated and proinflammatory CCR4+ CCR6+ Th17 in CD4 T-cells markedly increased." (PMID 34676126, 2020). "Although decreased blood lymphocyte count of COVID-19 patients has been widely reported, lymphocytes were shown to be activated as the increases in the expression of HLA-DR in CD4+ and CD8+ cells, the percentage of CD4+ CCR4+ CCR6+ Th17 cells." (PMID 32733921, 2020). "Interestingly, this same cell type is maintained at high levels even after the acute phase of COVID-19, especially within ‘naïve’ and TEMRA subsets, which could suggest extensive polarization of ‘naïve’ cells towards effector CCR6+CD8+ T cells." (PMID 36146713, 2022). "Thus, patients with severe COVID-19 showed a markedly high number of CCR6+ Th17 cells in peripheral blood, even though not all patients with severe COVID-19 have increased IL-17 expression." (PMID 35833134, 2022). "Hence, a long-term increase in peripheral blood CCR6- and CXCR5-expressing CD8+ T cells in COVID-19 convalescents revealed in our study might be considered one of the signals associated with long-COVID alterations in cytotoxic T cell subset composition." (PMID 36146713, 2022).
COVID-19 (continued). "Furthermore, using chemokine receptors as correlates of T helper subsets, we found that the frequency of Th1 equivalents (CCR6+CXCR3+) was unaltered between healthy controls, moderate and severe COVID-19 patients, but it was increased compared to convalescent individuals." (PMID 34745145, 2021). "Similar percentages of CD4+ T cells expressing CCR4, CCR6, CD161, CXCR3, TBET, and GATA3 were found among healthy donors and pregnant women with or without COVID-19." (PMID 34326336, 2021). "Next, we found that IL-27 negatively correlated with the CCR6+CD8+ T cell frequencies within EM (r = –0.400, p = 0.006) and TEMRA (r = –0.343, p = 0.021) subsets in patients with acute COVID-19, but not in convalescents COVID-19 or healthy controls (respectively)." (PMID 36146713, 2022).
breast cancer (33 papers, 2011 to 2026). A primary or metastatic malignant neoplasm involving the breast. "High expression of CCR6 significantly associated with worse overall breast cancer patient survival, but correlated with better survival in basal and HER enriched patients." (PMID 35754051, 2022). "CD31/CCR6-positive vessels were found associated with tumours of breast cancer and melanoma patients." (PMID 32601464, 2020). "We have thus established an essential role for CCR6 in the tumor microenvironment, providing a causative link between this receptor, infiltrating macrophages and mammary tumor development." (PMID 26047945, 2015). "In breast cancer, higher CCR6 expression levels were linked with tumor stage and grade, and incidence of metastasis to the pleura." (PMID 26047945, 2015). "We show here that the deletion of the chemokine receptor CCR6 caused a delay in tumor onset and decreased mammary tumor incidence in vivo in the MMTV-PyMT transgenic mouse model." (PMID 26047945, 2015). "What is more, the dysregulated genes IL2RG, IL6R, IL7R and TGFB2 have been reported to be associated with metastasis site or prognosis, and CCR6 is associated with both live metastasis in breast cancer and bone metastasis in human neuroblastoma." (PMID 25163697, 2014). "We noted significant declines in the level of several transcripts associated with metastasis (Cd36, Egr3, and Maf) and tumorigenesis (Ccr2 and Ccr6) in many solid tumors including breast cancer." (PMID 33682324, 2021). "It was shown that CCR6 was upregulated on TAMs and promoted the recruitment of proinflammatory macrophages in the mammary tumor microenvironment." (PMID 33919517, 2021). "For example, it is reported that CCL20, a ligand for CCR6, is abundant in PyMT mammary tumors and genetic deletion of Ccr6 gene in PyMT mice significantly reduces the number of TAMs in mammary tumors." (PMID 30483271, 2018). "In these studies, growth of mammary tumors in CCR6-knockout mice led to reduced mammary tumor initiation and growth." (PMID 26884646, 2016). "We therefore tested the potential link between the tumor-promoting function of CCR6 and breast cancer stem-like cell pools." (PMID 26047945, 2015). "In order to assess the impact of CCR6 on the later stages of cancerogenesis, MMTV-PyMT Ccr6WTand Ccr6−/− mice were sacrificed at 22–24 weeks of age and the total number of mammary tumors per mouse was determined." (PMID 26047945, 2015). "We then assessed the levels of macrophages in mammary tumors from MMTV-PyMT Ccr6WT and Ccr6−/− mice, and found that the proportion and overall numbers of TAMs were significantly reduced in MMTV-PyMT Ccr6−/− mammary tumors relative to Ccr6WT." (PMID 26047945, 2015). "Enumeration of macrophages within grafted tumors in Ccr6WT and Ccr6−/− mice paralleled the results seen in spontaneous mammary tumors." (PMID 26047945, 2015). "This study delineated for the first time a role for CCR6 in the development of breast cancer, and demonstrated a critical function for this receptor in maintaining the pro-tumorigenic cancer microenvironment." (PMID 26047945, 2015). "The results demonstrated that CCR6 promotes breast cancer initiation and progression through maintenance of pro-tumorigenic TAMs within tumor-bearing mammary glands, warranting further investigation of CCR6 as a possible therapeutic target." (PMID 26047945, 2015). "We have employed the well-characterized MMTV-PyMT transgenic mouse model of breast cancer, and have found that CCR6 facilitates an earlier tumor onset and an increased incidence of mammary tumors." (PMID 26047945, 2015). "We also investigated the effect of CCR6 ablation on functional stem-like mammary cancer cell pools using the mammosphere assay, which is used to select for colonies of early stem-like progenitors." (PMID 26047945, 2015). "The expression of the chemokine receptor CCR6 has been previously correlated with higher grades and stages of breast cancer and decreased relapse-free survival." (PMID 26047945, 2015).
breast cancer (continued). "We found that the deletion of CCR6 significantly reduced the initial hyperplastic outgrowth within the gland, a common indicator of future breast cancer development." (PMID 26047945, 2015). "Results presented in this study therefore suggest CCR6 as a potential target for therapeutic intervention in early breast cancer." (PMID 26047945, 2015). "We have also assessed CCR6 expression on B cells and specific T cell subsets (helper T cells (Th), cytotoxic T cells (Tc), and regulatory T cells (Treg)) within mammary tumors." (PMID 26047945, 2015). "We then sought to provide definitive evidence for the macrophage-mediating function of CCR6 in mammary tumor promotion using an in vivo macrophage reconstitution assay." (PMID 26047945, 2015). "The expression of CCR6 has been reported to correlate with higher stage and grade of human breast cancer, and has been proposed as a prognostic tool for determining relapse-free survival in breast cancer patients." (PMID 26047945, 2015). "Our previous study showed that CCR6+Treg cells were dominantly enriched in tumor mass and closely related to poor prognosis of breast cancer patients." (PMID 21655250, 2011). "The frequency of CCR6+Tregs in tumor infiltrating lymphocytes (TILs ) was analyzed at early stage and at late stage of tumor in a murine breast cancer model by FACS respectively." (PMID 21655250, 2011). "Here, we carefully evaluate the enrichment of CCR6+Tregs in tumor mass during progression of breast cancer and explore its possible mechanism." (PMID 21655250, 2011). "Our recent work further showed that CCR6+ subset of Treg cells were dominantly enriched in tumor mass and closely related to poor prognosis of breast cancer patients." (PMID 21655250, 2011). "Elevated CCL20 production and its receptor CCR6 have been related to the progression of a variety of human cancers, including liver cancer, colorectal cancer, breast cancer, and kidney cancer, and also indirectly modulates the function of immune cells in response to inflammatory diseases." (PMID 38468450, 2024). "Th17 CD25high cells accumulate in breast cancer tissue by recruitment via CCL20/CCR6." (PMID 35954312, 2022). "We found CCR6 is higher in luminal A and in triple negative than in luminal B breast cancers." (PMID 35754051, 2022). "Moreover, high CCL20/ CCR6 levels relate to stage and prognosis in many cancer types, including breast cancer, glioma, colorectal cancer, and non-small lung cancer." (PMID 33919517, 2021). "MiR-21 is highly expressed in CCR6+ Tregs in tumor tissues of patients with breast cancer." (PMID 34084160, 2021). "The upregulation of C-X-C motif ligand 16 (CXCL16) in human breast cancer cells exposed to IR resulted in a systemic surge of C-C motif chemokine receptor 6 (CCR6), expressed in NK cells through CXCL16–CCR6 interaction, which was abrogated in the presence of an anti-CXCR6 Ab." (PMID 32612950, 2020). "A recent publication implicates CCR6 in promoting breast cancer initiation and progression." (PMID 27335323, 2016). "Importantly, reconstitution of TAMs into CCR6-knockout mice bearing orthotopically transplanted MMTV-PyMT tumors restored tumor growth demonstrating the importance of this chemokine axis for mammary tumor growth." (PMID 26884646, 2016). "CCR6 deletion has also impeded recruitment of dendritic cells into PyMT-driven mammary tumors." (PMID 26047945, 2015). "We have also observed that the loss of CCR6 did not alter the numbers and functional properties of mammary cancer stem-like cells." (PMID 26047945, 2015). "In conclusion, we show here that CCR6 plays a significant role in the initiation and at the early stage of breast cancer development in vivo by mediating recruitment of pro-tumorigenic macrophages to the tumor site, and thus facilitating further progression to advanced stages of mammary neoplasia." (PMID 26047945, 2015).
breast cancer (continued). "Therefore, it is plausible to suggest that CCR6 in breast cancer functions to recruit pro-tumorigenic macrophages to the tumor immuniche, to support growth of transformed epithelial cells and cancer stem cells, as TAMs in the MMTV-PyMT model have also been shown to also maintain stem-like cells." (PMID 26047945, 2015). "Moreover, it was recently proposed that the presence of CCR6 may act as a prognostic factor for breast cancer patient survival." (PMID 26047945, 2015). "Specifically, in breast cancer, the chemokine receptors that exhibited the most significant correlations were CCR2, CCR4, CCR5, CCR6, CCR8, CXCR2, and CX3CR1." (PMID 40649753, 2025). "In breast cancer, tumor-derived CCL20 has been recently reported to signal on CCR6 in precursor macrophages, promote PMN-MDSC expansion and exert pro-tumor effects." (PMID 37398643, 2023). "For example, CCL20, increased in serum from animals with MLL tumors, has been shown to be highly expressed in breast cancer models, and inhibition of CCL20 expression or depletion of the CCL20 receptor gene (Ccr6) reduce macrophage infiltration in xenografts." (PMID 35551231, 2022). "In blood samples and invasive ductal carcinoma (IDC) tissue collected from breast cancer patients, Th17-related molecules (IL-17A, RORC, and CCR6), produced by tumor-infiltrating CD4+ and CD8+ T lymphocytes, were observed to be upregulated." (PMID 35954312, 2022). "CCR6+ Foxp3+ Treg are usually found in large numbers in the TME and are regarded as related to the poor prognosis of patients with breast cancer." (PMID 34084160, 2021). "Tissue sections of breast cancer and melanoma were double-stained for CD31 and CCR6 using immunofluorescence." (PMID 32601464, 2020). "Among this group of genes, aberrantly methylated in other human cancers were CCR6 in oral cancer and chronic lymphocytic leukemia, RAB37 in lung cancer, ZNF521 in breast cancer, and CDX1 in gastric cancer, esophageal SCC, and in colon cancer." (PMID 32961999, 2020). "In addition, CCL20/CCR6 may also be potential therapeutic targets for breast cancer." (PMID 31852159, 2019). "When CCR6 was deleted in the MMTV-PyMT mouse, tumor latency was significantly extended, and these mice developed fewer mammary tumors than their Ccr6WT counterparts." (PMID 26047945, 2015). "Some studies have indicated that tumor-secreted CCL20 activates granulocyte–monocyte progenitor cell differentiation through its receptor CCR6, leading to the expansion of PMN-MDSCs, which activates the CXCR2/NOTCH1/HEY1 signaling pathway to increase ALDH+ breast cancer tumor stem cells." (PMID 40722739, 2025). "Consistently, in the scRNA-seq analysis of the breast cancer microenvironment, CCR6 and CCR8 were predominantly expressed in lymphocytes, not fibroblasts." (PMID 36418470, 2023). "For example, some breast cancer cell lines have been shown to express CXCR4-CXCL12, CCR6." (PMID 28928458, 2017). "Altogether, these results demonstrate that the role of CCR6 in breast cancer is independent of breast epithelial and progenitor cells, raising the possibility that its mechanism of action involves the tumor microenvironment." (PMID 26047945, 2015). "MMTV-PyMT mammary tumor cells from Ccr6WT donor mice were purified and transplanted into the inguinal mammary fat pads of non-PyMT Ccr6WT and Ccr6−/− recipients at 5 weeks of age." (PMID 26047945, 2015). "In accordance with this, we found that a high proportion of macrophages within PyMT-driven mammary tumors express CCR6, which has not been previously demonstrated in breast cancer." (PMID 26047945, 2015). "Despite the significant role of TAMs in breast cancer, the expression and function of CCR6 within the macrophage population has not been shown within the mammary gland." (PMID 26047945, 2015). "Recent studies on breast cancers have shown that two of these chemokines, CCL20 and CCL22, may recruit Treg that express the corresponding chemokine receptors CCR6 and CCR4." (PMID 21521526, 2011).
breast cancer (continued). "In the present study, we showed that CCR6 +Tregs but not CCR6−Tregs were enriched in tumor mass during tumor progression in murine breast cancer model." (PMID 21655250, 2011). "In this study, we extended our pervious finding by demonstrating that CCR6+ Tregs, but not CCR6− Tregs were enriched in tumor mass during progression of breast cancer." (PMID 21655250, 2011). "We found that the prior enrichment of CCR6+Tregs but not CCR6−Tregs in tumor mass during progression of murine breast cancer, which was dependent on the dominant proliferation of CCR6+ Tregs in situ." (PMID 21655250, 2011). "Recently, we reported a Treg subset, CCR6+ Tregs but not CCR6−Tregs, were enriched in tumor mass and closely related to poor prognosis of breast cancer patients." (PMID 21655250, 2011). "In addition, ELAVL1 expression showed a strong positive correlation with CCL20 expression but not with CSF2 or CCR6 expression in breast cancer subtypes, particularly the basal-like subtype." (PMID 28851919, 2017). "This suggests that the role of CCR6 in breast cancer is independent of epithelial cells." (PMID 26047945, 2015). "Furthermore, the deletion of CCR6 did not lead to decreased numbers of Ki67-positive proliferating cells within intact tumor-bearing mammary glands, pointing to an epithelial-independent function of this receptor in breast cancer." (PMID 26047945, 2015). "In addition, there are other GPCRs and ligands that may recruit Tregs, such as CCR5/CCL5 in colorectal cancer (CRC) and pancreatic cancer, CCR6/CCL20 in HCC and breast cancer, and CCR10/CCL28 in ovarian cancer, while CXCR3 and CXCR6 are expressed by Tregs infiltrating renal cell carcinoma." (PMID 25110692, 2014). "The reconstitution of this CCR6-negative microenvironment with MMTV-PyMT Ccr6WT TAMs restored the tumor-promoting properties of mammary stroma, indicating that breast cancer can be therapeutically targeted through manipulation of the CCR6-CCL20 axis to control tumor-infiltrating macrophages." (PMID 26047945, 2015).